FCGR3B (Fc gamma receptor IIIb)
Diseases named in the same sentence as FCGR3B in open-access papers (continued):
Sharing a sentence is not in itself a finding about the gene and the disease.
malaria (6 papers, 2012 to 2023). Malaria is a serious and sometimes fatal disease caused by a parasite that commonly infects a certain type of mosquito which feeds on humans. "In this study, we explored the influence of Single Nucleotide Polymorphisms (SNP) in exon 4 of FCGR2A and in exon 3 of FCGR3B in a cohort of Beninese infants followed-up for malaria from birth to 24 months of age." (PMID 36499205, 2022). "Our results highlight the impact of FCGR3B polymorphisms on the individual susceptibility to malaria and antibody responses against MSP3 and GLURP in Beninese children." (PMID 36499205, 2022). "Three additional polymorphisms of the FCGR3B gene were also considered in this study: 197 G > T, 297 G > T and 371 A > G, of which were previously associated with protection from malaria." (PMID 36499205, 2022). "Most of the socio-demographic factors, malaria antigen-specific antibodies and the FCGR3B variant used in this study as predictors have been found to be associated with clinical malaria in various malaria seroepidemiological studies." (PMID 32854708, 2020). "Using a more rigorous prediction modelling approach, this study aims to evaluate the predictive performance of malaria antibodies and FCGR3B gene polymorphisms on P. falciparum infection outcome." (PMID 32854708, 2020). "This study has found that the FCGR3B-c.233C>A genotype and IgG against AMA1 were relatively better compared to the other antibodies and FCGR3B genotypes in classifying or predicting malaria risk among children." (PMID 32854708, 2020). "This study found that the FCGR3B-c.233C>A genotype and IgG against AMA1 were relatively better compared to the other antibodies and FCGR3B genotypes studied in classifying or predicting malaria risk among children." (PMID 32854708, 2020). "The study investigated the predictive performance of several malaria-specific antibodies (IgG and subclasses) and FCGR3B polymorphisms on the malaria risk." (PMID 32854708, 2020). "The A-allele of FCGR3B-c.233C>A (rs5030738) was significantly associated with protection from clinical malaria under two out of three genetic models (additive: p = 0.0061; recessive: p = 0.097; dominant: p = 0.0076) of inheritance." (PMID 23049979, 2012). "Using PCR-ASRED and exon 3 nucleotide sequencing data for FCGR2A and FCGR3B respectively, the association between SNPs which alter the affinity of these receptors for IgG subclasses and clinical malaria were studied in a cohort of Ghanaian children." (PMID 23049979, 2012). "The c.233A-allele of FCGR3B which was associated with protection from clinical malaria in the present study causes a replacement of the hydrophobic amino acid alanine (A) with the negatively charged aspartic acid (D) at position 78 in the NA2 protein." (PMID 23049979, 2012). "Genetic polymorphisms present in FCGR2A and FCGR3B genes could alter the affinity of FcgRIIA and FcgRIIIB receptors for IgG, and therefore, influence the quality of the immune response against malaria." (PMID 36499205, 2022). "Although most of the antibodies did not improve the performance of the baseline model, it is worth noting that AMA1 specific antibodies and FCGR3B-c.233C>A under the additive and dominant models of inheritance, can discriminate children of low and higher risk of malaria." (PMID 32854708, 2020). "Single marker association of FCGR3B alleles with clinical malaria." (PMID 23049979, 2012). "Therefore, the association observed between malaria susceptibility and this haplotype could result from the presence of the A-allele at position 194 of FCGR3B." (PMID 36499205, 2022). "It has recently been shown that interaction between naturally acquired antibodies to Plasmodium falciparum and polymorphisms in host FCGR3B gene, encoding the Fc Gamma Receptor IIIB (FcγRIIIB) plays a key role in immunity against malaria." (PMID 32854708, 2020).
malaria (continued). "The findings support Apical Membrane Antigen 1 as an important malaria vaccine antigen while FCGR3B-c.233C>A under the additive and dominant models of inheritance were also identified as an important modifier of the effect of malaria protective antibodies." (PMID 32854708, 2020). "The prognosis in this study is based on the child’s baseline socio-demographic characteristics, blood group, sickle cell status, the use of bed net, presence of malaria parasite in blood and malaria-specific antibodies and FCGR3B genotype." (PMID 32854708, 2020). "In conclusion, the present study has identified the c.233A allele of FCGR3B-c.233C>A (rs5030738) and the FcγRIIIB-SH (CTGAAA) haplotype to be associated with protection from clinical malaria." (PMID 23049979, 2012). "In the present study, we successfully elucidated associations between FCGR3B and FCGR2A polymorphisms and clinical malaria using data from a well characterised longitudinal cohort study." (PMID 23049979, 2012). "Individuals of the Ewe ethnic group showed a reduced risk to clinical malaria compared to other ethnic groups, however, the distribution of genotypes was not different between the ethnic groups except for FCGR2A-497A>G and FCGR3B-194A>G." (PMID 23049979, 2012). "FCGR3B-exon 3 was sequenced in 585 children, aged 1 to 12 years living in a malaria endemic region of Ghana." (PMID 23049979, 2012). "The data supports the P. falciparum, AMA1 as an important malaria vaccine antigen, while FCGR3B-c.233C>A under the additive and dominant models of inheritance could be an important modifier of the effect of malaria protective antibodies." (PMID 32854708, 2020). "Here, using FCGR3B-exon 3 nucleotide sequencing data, we find a previously reported variant of FcγRIIIB-NA2, FcγRIIIB-NA2*03 (associated gene: FCGR3B*02A244G,) to be associated with susceptibility to clinical malaria." (PMID 23049979, 2012).
periodontitis (6 papers, 2021 to 2025). An acute or chronic inflammatory process that affects the tissues that surround and support the teeth. "Respective FCGR3B polymorphisms have been comprehensively studied in the context of periodontitis, whereby a meta-analysis showed that such a polymorphism is related with a nearly three-fold higher risk of developing an aggressive periodontitis." (PMID 37510279, 2023). "Moreover, FCGR3B was found to be one key gene associated with oxidative stress in periodontitis, which could be of certain relevance in the interplay between periodontitis and CKF." (PMID 37510279, 2023). "Similar to CCL5, FCGR3B supports the link between periodontitis and CKF via increased pro-inflammation." (PMID 37510279, 2023). "Periodontitis and CKF show genetic cross-talk, which is supported by five hub genes, i.e., CCL5, FCGR3B, MMP-9, SAA1, and SELL." (PMID 37510279, 2023). "In the present study, by performing multiple bioinformatics analysis methods, we firstly identified six key OS-genes (CXCR4, SELL, FCGR3B, FCGR2B, PECAM1, and ITGAL) in periodontitis, whose expression levels were significantly upregulated." (PMID 36148415, 2022). "Six of them were identified as key OS-genes (CXCR4, SELL, FCGR3B, FCGR2B, PECAM1, and ITGAL) in periodontitis." (PMID 36148415, 2022). "The 115 DEPs revealed 4 significantly enriched pathways (p value<0.05) in which Staphylococcus aureus infection signalling pathway, including FCGR3B and HLA-DPA1, exhibited a significant difference in gingival tissues from healthy and periodontitis groups." (PMID 36016933, 2022). "Similar to FCGR3B, SELL was found to be a gene related to oxidative stress in periodontitis." (PMID 37510279, 2023). "In conclusion, five hub cross-talk genes, i.e., CCL5, FCGR3B, MMP-9, SAA1, and SELL, could be involved in the interplay between periodontitis and CKF, whereby primarily inflammation, metabolic, and vascular issues appear to be of relevance." (PMID 37510279, 2023).
Autoimmunity (5 papers, 2011 to 2022). The occurrence of an immune reaction against the organism's own cells or tissues. "A number of candidate autoimmune genes of which some have been reported to have CNV associated with autoimmunity (e.g. FCGR3B), were tested for association to AD." (PMID 21851588, 2011). "In particular, FCGR3B CNV has been investigated in risk of autoimmunity." (PMID 25452756, 2014). "FCGR2A-131R and FCGR2B-232T have been implicated in increased risk of systemic lupus erythematous, while FCGR3B HNA 1B and decreased copy number of FCGR3B have been associated with reduced immune complex clearance and increased risk of autoimmunity." (PMID 30899264, 2019). "Association between FCGR3B CNV and a number of autoimmune disorders has been reported in European populations, including SLE, RA, and in Japanese population for ulcerative colitis." (PMID 25452756, 2014). "The possible explanation for this association could be the potentially impaired interaction of low FCGR3B with autoantigen-autoantibody immune complexes, ultimately contributing to autoimmunity." (PMID 36553504, 2022).
primary Sjogren's syndrome (5 papers, 2010 to 2019). "Another difference between SLE on the one hand and KD and ITP on the other hand is that SLE is associated with low copy number of FCGR3B (as is Sjögren syndrome, systemic sclerosis and possibly RA)." (PMID 31632391, 2019). "FCGR3B CN variation has become established as a risk factor for a range of systemic autoimmune diseases, including RA, Sjögren's syndrome, and SLE." (PMID 23864940, 2013). "Its occurrence in our patients with the last Stage IV of SA is in agreement with observations of increased CN of FCGR3B gene in patients with IPF, patients of Spanish ancestry with SLE and primary Sjögren’s syndrome, British patients with AASV and Han Chinese patients with psoriasis vulgaris." (PMID 28472129, 2017).
vasculitis (4 papers, 2011 to 2014). "In contrast, given the importance of neutrophil activation in vascular inflammation, it is plausible that high FCGR3B copy number may in fact predispose to receptor-mediated neutrophil activation and therefore vasculitis." (PMID 24027635, 2013). "Previous studies have reported intriguing, but conflicting, relationships between FCGR3B copy number and vasculitis in the context of different diseases." (PMID 24027635, 2013). "Other studies have reported intriguing but conflicting relationships between FCGR3B CN and vasculitis in the context of different diseases." (PMID 22701122, 2012). "Previous studies in relation to FCGR3B CNV and vasculitis are inconclusive." (PMID 24027635, 2013).
Kawasaki disease (3 papers, 2013 to 2017). A rare inflammatory disease characterized by an acute febrile, systemic, self-limiting, medium-vessel vasculitis primarily affecting children. "The FCGR2A-H131 variant associates with susceptibility to Kawasaki Disease, whereas responsiveness to IVIG therapy in Kawasaki Disease patients is strongly associated with the FCGR3B genotype: the NA1 variant significantly decreases the odds of an appropriate clinical outcome." (PMID 24910634, 2014). "However, in Kawasaki disease (KD) a low copy number of FCGR3B gene was considered as protective factor against the disease development, pointing to an increased CN of this gene as a risk factor for KD." (PMID 28472129, 2017). "Similarly, CNV of both FCGR3B and FCGR2C were associated with Kawasaki Disease susceptibility and influenced IVIG treatment response." (PMID 24910634, 2014). "While we were unable to demonstrate an association between FCGR3B copy number and GCA in this study, there are putative links to polymorphism in this region with systemic vasculitides, as SNPs within the FCGR gene cluster have been associated with GCA, Behcet's diseases and Kawasaki's disease." (PMID 24027635, 2013).
microscopic polyangiitis (3 papers, 2011 to 2017). Microscopic polyangiitis (MPA) is an inflammatory, necrotizing, systemic vasculitis that affects predominantly small vessels (i.e. small arteries, arterioles, capillaries, venules) in multiple organs. "Other authors have found a decreased CN of FCGR3B gene in SLE, RA, GPA, microscopic polyangiitis, AASV, pSS and systemic sclerosis." (PMID 28472129, 2017).
sarcoidosis (3 papers, 2017 to 2023). Sarcoidosis is a multisystemic disorder of unknown cause characterized by the formation of immune granulomas in involved organs. "We have found a lack of association between copy number of FCGR2A, FCGR2B, FCGR2C, FCGR3A, FCGR3B genes and risk of development of sarcoidosis in our patients." (PMID 28472129, 2017). "Additionally, the presence of higher IC-binding variants of FCGR2A and FCGR3B genes in individuals with advanced stages of SA vs. TB patients, can help to predict if sarcoidosis will progress to a more severe disorder and serve as a marker of SA prognosis." (PMID 37174624, 2023). "CNV of FCGR3A gene occurred in 13.46% of SA patients and 18.18% of healthy controls, whereas CNV of FCGR3B gene was present in 29.13% of patients with sarcoidosis and in 22.43% of the controls." (PMID 28472129, 2017). "We have detected only a relevant increase in CN of FCGR2C and FCGR3B in the last Stage IV of sarcoidosis vs. other stages and controls, but this observation was based on a limited number of six patients classified to Stage IV of SA." (PMID 28472129, 2017). "A relevant increase in copy number of FCGR2C and FCGR3B in Stage IV of sarcoidosis vs. other stages and controls was detected, but this observation was based on a limited number of Stage IV patients." (PMID 28472129, 2017). "Therefore, we have analyzed polymorphism of these genes in our SA patients and revealed that, in contrast to polymorphism of FCGR2B and FCGR3B, polymorphism of FCGR2A, FCGR2C and FCGR3A may contribute to immunocomplexemia present in sarcoidosis." (PMID 28472129, 2017). "Enriched genes including MPO (myeloperoxidase), CXCL11, IL1A, CXCL10, FCGR3B, IL1B, TTN (titin), BATF2, VIP (vasoactive intestinal peptide), TLR3, CCR2, TLR7, and CR1 wereclosely related to sarcoidosis." (PMID 38137330, 2023).
Sepsis (3 papers, 2021 to 2025). Sepsis is defined as life-threatening organ dysfunction caused by a dysregulated host response to infection. "The ROC curve analysis revealed that ITGAM, CXCR2, and FCGR3B exhibited high classification accuracy (AUC >0.9) between the Sepsis and Control groups, indicating their strong potential for early diagnosis." (PMID 41259376, 2025). "FCGR3B, which encodes a receptor for the Fc region of immunoglobulin G, is involved in ADCC and has been shown to influence the severity of sepsis." (PMID 41259376, 2025). "Receiver operating characteristic (ROC) curve analysis demonstrated that ITGAM, CXCR2, and FCGR3B exhibited extremely high accuracy in distinguishing sepsis from controls (with an area under the curve greater than 0.9)." (PMID 41259376, 2025). "FCGR3B not only showed upregulated expression in sepsis but was also elevated in other inflammatory diseases, indicating potential nonspecificity as a diagnostic biomarker." (PMID 41259376, 2025). "Next, the ROC curves show that the ITGAM, CXCR2, and FCGR3B expression levels provide high accuracy for classifying the Sepsis and Control group (AUC > 0.9); MMP9, MPO, and CTSG expression levels exhibit moderate accuracy for this classification (0.7 < AUC < 0.9)." (PMID 41259376, 2025).
staphylococcus aureus infection (3 papers, 2020 to 2022). An infectious process in which the bacteria Staphylococcus aureus is present. "Gene FCGR1A, FCGR3A, and FCGR3B were enriched in both the staphylococcus aureus infection and osteoclast differentiation pathways, and belong to the Fc gamma receptor (FcγR), a receptor for the Fc portion of IgG." (PMID 33344459, 2020). "Then, LYN, FCGR3A, and FCGR3B are involved in “module 1” of the subnetwork, in which GO functional annotation is enriched in inflammatory response and immune response, and KEGG pathway enrichment analysis is enriched in staphylococcus aureus infection, phagosome, and osteoclast differentiation." (PMID 32733557, 2020).
systemic sclerosis (3 papers, 2014 to 2019). A chronic disorder, possibly autoimmune, marked by excessive production of collagen which results in hardening and thickening of body tissues. "A recent study showed that impaired immune complex clearance arising from FCGR3B deficiency contributes to the pathology of systemic sclerosis, and FCGR3B copy number variation is a common risk factor for systemic autoimmunity." (PMID 25331815, 2014).
Behçet's disease (2 papers, 2012 to 2013). "We have also previously reported that FCGR3B CNV is not a risk factor for Behcet's disease in Iranian patients." (PMID 24027635, 2013).
breast carcinoma (2 papers, 2020 to 2024). "Moreover, we found six sex-biased genes (EGFR, CDK6, PRKCB, PDCD1, KCNH2, FCGR3B, and TOP2A) in BRCA were the therapeutic targets of breast cancer." (PMID 39175079, 2024).
chronic obstructive pulmonary disease (2 papers, 2024). A chronic and progressive lung disorder characterized by the loss of elasticity of the bronchial tree and the air sacs, destruction of the air sacs wall, thickening of the bronchial wall, and mucous accumulation in the bronchial tree. "A reduction in FCGR3B gene dosage was linked with a higher risk of developing chronic obstructive pulmonary disease (COPD)." (PMID 39345014, 2024). "FCGR3B deletion has previously been associated with several autoimmune disorders; in this study, decreasing FCGR3B gene dosage was also associated with an increasing risk of chronic obstructive pulmonary disease (P = 7.5 × 10−7)." (PMID 38548989, 2024).
lupus nephritis (2 papers, 2013 to 2025). Glomerulonephritis in the context of systemic lupus erythematosus. "We conducted a detailed analysis of the association between FCGR2A, FCGR2B, FCGR3A and FCGR3B polymorphisms and lupus nephritis." (PMID 40728959, 2025).
renal cell carcinoma (2 papers, 2020 to 2022). "The function of FCGR3B is associated with the innate immune system, renal cell carcinoma, and antiglomerular basement membrane antibody disease (anti-GBM disease)." (PMID 32596394, 2020). "From the CellMarker website, we got 4 cell markers of neutrophils in renal cell carcinoma, and by GEPIA, we found FCGR3B and MNDA are significantly highly expressed in ccRCC tumor samples; SELL is also relatively highly expressed though without statistical significance." (PMID 35299868, 2022).
Alzheimer disease (1 paper, 2023). A progressive, neurodegenerative disease characterized by loss of function and death of nerve cells in several areas of the brain leading to loss of cognitive function such as memory and language. "FCGR3B-targeted drug IMGATUZUMAB was currently being evaluated in clinical trials for colorectal neoplasms, head and neck neoplasms, and non-small-cell lung and PED4D inhibitor was currently being evaluated in clinical trials for Alzheimer’s disease, fragile X syndrome, and depression." (PMID 37775746, 2023).
bladder cancer (1 paper, 2025). "This implies that Neu-FCGR3B might negatively influence the anti-tumor response and could serve as a potential predictive marker for bladder cancer." (PMID 40367012, 2025). "Neu-FCGR3B may play a detrimental role in the anti-tumor response and could emerge as a predictive marker for bladder cancer." (PMID 40367012, 2025).
cerebral malaria (1 paper, 2012). A sequestration of Plasmodium falciparum in the brain, which can cause coma and/or seizures. "Association studies based on Polymerase Chain Reaction-Sequence Specific Primer (PCR-SSP) data of FCGR2A and FCGR3B have found individuals carrying the NA2 allotype in combination with FcγRIIA-166H have an increased risk of developing cerebral malaria and severe malarial anaemia." (PMID 23049979, 2012).
chronic hepatitis B (1 paper, 2024). "A deficiency of the FCGR3B gene has been shown to increase the risk of chronic hepatitis B." (PMID 38809509, 2024).